TGFB2 (transforming growth factor beta 2)
Diseases named in the same sentence as TGFB2 in open-access papers (continued):
Sharing a sentence is not in itself a finding about the gene and the disease.
Aortic root aneurysm (3 papers, 2014 to 2018). An abnormal localized widening (dilatation) of the aortic root. "Tgfb2+/− mice showed dilatations of the aortic annulus and aortic root, a pattern similar to that of LDS and MFS patients, confirming that loss‐of‐function of one Tgfb2 allele is sufficient to cause aortic root aneurysm." (PMID 29392890, 2018).
cholangiocarcinoma (3 papers, 2016 to 2025). A carcinoma that arises from the intrahepatic biliary tree (intrahepatic cholangiocarcinoma) or from the junction, or adjacent to the junction, of the right and left hepatic ducts (hilar cholangiocarcinoma). "We found that the expression of TGFβ2 was significantly elevated relative to normal controls in cholangiocarcinoma (CHOL), colon adenocarcinoma (COAD), liver hepatocellular carcinoma (LIHC), stomach adenocarcinoma (STAD) and thyroid carcinoma (THCA)." (PMID 32530106, 2020). "For example, distinct peptide mass fingerprints (PMFs) were identified for early versus late recurrence in cholangiocarcinoma (CCA), where peptides such as KNTC1, DCLK1, ALG10, ATR, and BLM were associated with early recurrence, while SERPINA1, TGFB2, and SERPING1 were implicated in late recurrence." (PMID 41008874, 2025).
cleft palate (3 papers, 2015 to 2016). Cleft palate is a fissure type embryopathy that affects the soft and hard palate to varying degrees. "This has been shown by deletions of TGFβ2, TGFβ3 and Inhibin βA, which all result in cleft palate defects in the respective mouse model." (PMID 26447543, 2015).
COVID-19 (3 papers, 2020 to 2022). A disease caused by infection with severe acute respiratory syndrome coronavirus 2. "We also found that the elevated pro-inflammatory cytokines (IFNGR1, IFNGR2, and TGFB2) were significantly co-expressed with ACE2 in male squamous cells from critically ill COVID-19 patients." (PMID 34330889, 2021).
esophageal squamous cell carcinoma (3 papers, 2021 to 2025). Esophageal squamous cell carcinoma (ESCC) is a type of esophageal carcinoma (EC) that can affect any part of the esophagus, but is usually located in the upper or middle third. "focused on the mechanism of TGFβ2 in promoting esophageal squamous cell carcinoma (ESCC) metastasis." (PMID 34386431, 2021). "In addition, miR-627-3p could inhibit the expression of TGFB2 and the secretion of TGF-β, which leads to the downregulation of ZEB1 and the suppression of EMT in esophageal squamous cell carcinoma." (PMID 35322735, 2022).
gallbladder cancer (3 papers, 2022 to 2025). "In addition, gallbladder cancer has shown an association between EMT and TGFβ2 in cancer metastasis, suggesting the possibility of specific actions of TGFβ2 in various cancers." (PMID 39992949, 2025). "Furthermore, miR-324-5p inhibited gallbladder carcinoma cell metastatic behaviors by downregulating transforming growth factor beta 2 expression." (PMID 37036350, 2023).
Hernia (3 papers, 2022 to 2025). "metaUSAT met-analysis yielded a further candidate gene at 1q41 (TGFB2) which was also the most statistically significant locus in the umbrella hernia analysis." (PMID 36584111, 2022). "Additionally, the presence of fibroblasts that coexpress PGR and TGFB2 in human hernia tissue suggests that Pgr+ fibroblast-driven TGF-β2 secretion could play a role in human LAM fibrosis." (PMID 40504614, 2025). "Pgr+ fibroblasts likely play a central role in this process of hernia development, as they are upregulated in EP LAM and have increased expression of Tgfb2, Tgfbr1, and Tgfbr2." (PMID 40504614, 2025). "Expression levels of both TGFBR2 and TGFB2 were significantly increased in herniated LAM tissue compared with matched healthy LAM tissue, suggesting that increased TGF-β signaling in LAM tissue may contribute to hernia development in humans." (PMID 40504614, 2025).
hypertrophic cardiomyopathy (3 papers, 2015 to 2024). A condition in which the myocardium is hypertrophied without an obvious cause. "The echocardiography of the son carrying the TGFB2 variant (patient A) did not reveal any aortic dilatation or valvular heart disease but hypertrophic cardiomyopathy with asymmetric thickening of the interventricular septum." (PMID 32154675, 2020).
keratoconus (3 papers, 2011 to 2015). A degenerative, structural disorder of the eye, characterized by a cone-shaped protrusion of the cornea. "By IHC staining we had also detected increased staining of TGFβ2 and pSMAD2/3 in the epithelial layers of keratoconus corneas, but had not tested pSMAD1/5/8 in that study." (PMID 25247416, 2014).
macular degeneration (3 papers, 2020 to 2024). Loss of vision in the central portion of the retina (macula), secondary to retinal degeneration. "Among them, four Hyper-LGs (CKB, PPP3CA, TGFB2, and SOCS2) overlapped with risk genes in the category of “macular degeneration” in the PHGKB." (PMID 32209064, 2020).
malaria (3 papers, 2010 to 2023). Malaria is a serious and sometimes fatal disease caused by a parasite that commonly infects a certain type of mosquito which feeds on humans. "It should be noted that according to our observations the replication of TGFB2 specific association to CM in other populations is expected to be stronger when analyzed in the context of severe malaria." (PMID 20585394, 2010). "We report that the clinical outcome of P. falciparum infection in a cohort of Angolan children (n = 430) correlated with nine TGFB2 SNPs that modify the risk of progression to CM as compared to other severe forms of malaria." (PMID 20585394, 2010). "Studies of TGFB2 haplotypes in other populations and areas with different malaria endemicity would be required to determine whether the TGFB2 genetic variance represents a widespread CM risk factor." (PMID 20585394, 2010). "These transcripts belong to three genes: IFIH1, TGFB2 and PRKCA, and are associated with three KEGG pathways all related to infection and infection detection (RIG-I-like receptor signaling pathway, Malaria, and African trypanosomiasis)." (PMID 38161589, 2023). "Thus the TGFB2 gene was identified as a candidate gene to CM susceptibility in a genetic cross that used wild-derived mouse strains and where CM susceptibility segregated from hyperparasitaemia, suggesting that TGFB2 would be a gene conferring risk to CM in the context of severe malaria." (PMID 20585394, 2010). "Although these factors limit the extrapolation of the association results to other populations our findings suggest the novel hypothesis that in African populations the TGFB2 and HMOX1 genetic variation correlate with malaria genetic susceptibility." (PMID 20585394, 2010). "Within the malaria pathway, miR-193b promotes the THBS1, THBS2, and TGFβ2 genes; and regulates apoptosis by targeting myeloid leukaemia cell differentiation protein 1, among others." (PMID 29747626, 2018).
metastatic tumor (3 papers, 2019 to 2022). "This difference in metastatic tumor location was attributed to the expression of transforming growth factor-beta 2 (TGF-β2) in cancer cells: TGF-β2 mRNA was highly expressed by the K-1735 cells, whereas the B16 cells or B16 x K-1735 cell mixes had low expression." (PMID 31481958, 2019).
Miscarriage (3 papers, 2022 to 2026). A pregnancy that ends at a stage in which the fetus is incapable of surviving on its own, defined as the spontaneous loss of a fetus before the 22th week of pregnancy. "In this study, we expect to explore the association, causality, and underlying mechanism among lnc‐HZ05, TGFβ2 signaling, trophoblast cell migrasome formation, and unexplained miscarriage." (PMID 41168951, 2026). "Multivariate logistic regression analysis by adjusting for all the variables and ROC curve analysis showed that the protein levels of TGFβ2, TGFβR2, Smad3, and p‐Samd3 were all negatively associated with miscarriage." (PMID 41168951, 2026). "In this study, we find that TGFβ2‐mediated MF is suppressed and is negatively associated with RM based on a case‐control study, further confirmed by a mouse model with miscarriage." (PMID 41168951, 2026). "Therefore, the (TGFβ2‐TGFβR2)/Smad3/pSmad3 signaling pathway was suppressed in RM versus HC villous tissues and this suppressed pathway was associated with miscarriage." (PMID 41168951, 2026). "TGFβ2 signaling might be associated with trophoblast cell migrasome formation and miscarriage." (PMID 41168951, 2026). "TGFβ2 signaling‐mediated migration/invasion and migrasome formation are suppressed in recurrent miscarriage (RM) versus healthy control villous tissues and are negatively associated with unexplained RM." (PMID 41168951, 2026). "In this study, we find that TGFβ2 signaling is suppressed in RM versus HC villous tissues and in placental tissues of a mouse miscarriage model." (PMID 41168951, 2026). "In details, lnc‐HZ05 suppresses FOXP3‐mediated TGFβ2 mRNA transcription, promotes autophagy degradation of TGFβ2 protein, impairs TGFβ2/TGFβR2 protein interactions, and eventually induce unexplained miscarriage." (PMID 41168951, 2026). "In a mouse miscarriage model, supplement with murine Tgfβ2 protein promotes migration/invasion and migrasome formation in placenta and efficiently alleviate mouse miscarriage." (PMID 41168951, 2026). "In mouse miscarriage model, murine (Tgfβ2‐Tgfβr2)/Smad3/p‐Samd3 signaling in placental tissues are down‐regulated." (PMID 41168951, 2026). "Based on the assays using human trophoblast cells, RM and HC villous tissues, and placental tissues of a mouse miscarriage model, we find that lnc‐HZ05 specifically suppresses TGFβ2‐promoted trophoblast cell migrasome formation and thus induces miscarriage." (PMID 41168951, 2026). "Taken together, this study discovers novel epigenetic mechanisms how a lncRNA regulates TGFβ2 signaling, enriching the upstream regulatory mechanism of TGFβ2, a potential target for treatment against miscarriage." (PMID 41168951, 2026). "This study not only discovers novel regulatory roles of lnc‐HZ05 and TGFβ2 pathway in the pathogenesis of unexplained miscarriage but also provides potential targets for prediction of and treatment against unexplained miscarriage." (PMID 41168951, 2026). "This study not only discovers novel biological mechanisms of lnc‐HZ05 and TGFβ2 signaling in the pathogenesis of unexplained miscarriage but also provides potential targets for prediction of and treatment against unexplained miscarriage." (PMID 41168951, 2026). "TGFβ2 expression was detected to be lower in trophoblastic and decidual cells from miscarriages when compared to uncomplicated pregnancies." (PMID 36550096, 2022). "The serum levels of TGFβ2 protein are lower and that of lnc‐HZ05 are higher in RM versus HC group and could predict miscarriage risk." (PMID 41168951, 2026). "Supplement with murine Tgfβ2 protein recovers MF and alleviates mouse miscarriage." (PMID 41168951, 2026). "Herein, whether TGFβ2 might regulate trophoblast cell migrasome formation (MF) and miscarriage, and the epigenetic regulation mechanisms, is completely unknown." (PMID 41168951, 2026). "Moreover, the roles of TGFβ2 signaling in trophoblast cell migrasome formation and miscarriage are completely unknown and should be fully investigated." (PMID 41168951, 2026).
Miscarriage (continued). "Moreover, higher levels of TGFβ2 protein and lnc‐HZ05 in serum well predict miscarriage risk." (PMID 41168951, 2026). "Supplement with recombinant murine Tgfβ2 protein could efficiently recover Tgfβ2 pathway, restore migration/invasion and migrasome formation in mouse placenta, and further alleviate mouse miscarriage, providing an efficient approach for treatment against miscarriage." (PMID 41168951, 2026). "Moreover, whether TGFβ2 might be used for miscarriage treatment has never been explored." (PMID 41168951, 2026).
oral cancer (3 papers, 2021 to 2026). "Among a cohort of 80 oral leukoplakias evaluated by IHC for immunomodulatory mediators, increased expression of HLA-G/E, IL10, TGFβ2/3 was noted when compared with oral carcinoma samples." (PMID 36860910, 2021). "By translating the most significantly expressed gene matrix into clinical datasets of oral cancer tissues, we showed that the summed expression of FN1, TGFB2, TGFBR2, and TGFBI, dubbed the CAF index, is a poor indicator of overall survival for oral cancer (n=40) and the PANCAN (n=9,356) cohorts." (PMID 34869001, 2021).
rheumatoid arthritis (3 papers, 2016 to 2025). A chronic, systemic autoimmune disorder characterized by inflammation in the synovial membranes and articular surfaces. "We evaluated PDGFA, TGFB1, TGFB2, and TGFB3 role in the diagnosis of ILD associated with rheumatoid arthritis (RA), systemic sclerosis (SSc), and inflammatory myopathies (IM)." (PMID 41226758, 2025). "Furthermore, several genes that were annotated in studies on rheumatoid arthritis (VEGFA, TGFB2, MMP1, MMP3, IL8, CCL3L1, CTSL1, CCL2) were also significantly upregulated in the immature articular cartilage in our study." (PMID 27045355, 2016).
serous ovarian cancer (3 papers, 2020 to 2025). "Therefore, serous ovarian cancer patients with high TGFB2 expression and low expression of associated markers showed improved OS." (PMID 41465326, 2025). "We performed the qRT-PCR analysis of TGFβ components (TGFB1, TGFB2, TGFBR1, TGFBR2), Wnt5A/ROR1/ROR2, and Hippo-related genes (YAP1, TAZ, CCN1, and CCN2) in serous ovarian cancer subtypes (LGSOC, HGSOC, BLSOC) compared to the normal ovary." (PMID 35053353, 2022).
systemic sclerosis (3 papers, 2019 to 2025). A chronic disorder, possibly autoimmune, marked by excessive production of collagen which results in hardening and thickening of body tissues. "A previous report has additionally found an association between TGFβ2, TGFβ3, and TIMP1 in systemic sclerosis, which may ultimately be due to the contribution of IGF-II, based on the results of this study." (PMID 31765403, 2019). "In patients suffering from systemic sclerosis, the anti-TGFB monoclonal antibody fresolimumab, which targets the 3 TGFB isoforms (TGFB1, TGFB2, and TGFB3), was shown to be well tolerated and clinically efficient in a phase II clinical trial." (PMID 31779094, 2019).
bipolar disorder (2 papers, 2024). A disorder of the brain that causes unusual shifts in mood, energy, activity levels and the ability to carry out day-to-day tasks. "Another study also found that promoter DNA hypomethylation of TGFB2 in the postmortem brains of patients with schizophrenia and bipolar disorder is associated with its increased expression." (PMID 38994948, 2024). "In contrast to bipolar disorder, increased expression of SLC1A2 (along with TGFB2) has been linked to schizophrenia pathogenesis." (PMID 38994948, 2024). "Another study reported that increased TGFB2 expression in post-mortem brains of patients with SCZ and bipolar disorder is due to its promoter DNA hypomethylation." (PMID 38398057, 2024).
Camurati-Engelmann disease (2 papers, 2021 to 2022). Camurati-Englemann disease (CED) is a rare, clinically variable bone dysplasia syndrome characterized by hyperostosis of the long bones, skull, spine and pelvis, associated with severe pain in the extremities, a wide-based waddling gait, joint contractures, muscle weakness and easy fatigability. "Targeted deletion of the TGFβ2 gene product alters the overall size and shape of limb rudiments, and naturally occurring mutations in the TGFβ2 gene cause Camurati-Engelmann Disease, characterized by thickening of the long bone collar." (PMID 35465334, 2022).
coloboma (2 papers, 2018 to 2021). An abnormality in which a part of a structure in one or both eyes is missing. "As of now, however, further research and identification of additional coloboma cases with pathogenic TGFB2 variants are needed to elucidate the role of TGFB2 in coloboma." (PMID 33418956, 2021). "Our results suggest that TGFB2 mutations in humans may result in developmental eye anomalies such as coloboma, as seen in mice." (PMID 33418956, 2021). "We identified a coloboma phenotype in the TGFβ2 knockout (KO) mouse, with TGFβ ligands expressed in the zebrafish eye, and the ligand binding receptor expressed within the fissure where we also found active TGFβ signalling." (PMID 29593116, 2018). "We identified a coloboma in mice with a targeted inactivation of transforming growth factor β2 (TGFβ2)." (PMID 29593116, 2018). "However, Tgfb2 knockout mice were shown to exhibit numerous developmental defects, including coloboma, while Tgfb2 inhibition via BMP signaling was shown to prevent optic fissure closure." (PMID 33418956, 2021). "Notably, we found marked, severe coloboma phenotypes in both TGFβ2 KO as well as in TGFβ2/GDNF double KO conditions." (PMID 29593116, 2018). "Secondly, the marked, strong coloboma phenotypes can be observed in both TGFβ2−/− GDNF−/− and TGFβ2−/− GDNF+/+ embryos from a mixed breeding background, occasionally also presenting a dorsal coloboma, while the phenotype of TGFβ2 KO embryos from a sole breeding background is noticeably milder." (PMID 29593116, 2018). "To this end we compared RNA harvested from eyes of wild-type embryos and TGFβ2/GDNF double mutant embryos, in which the coloboma phenotype was assigned to TGFβ2 function." (PMID 29593116, 2018). "TGBβ2-dependent coloboma was first observed in TGFβ2/GDNF double mutants (, Rahhal & Heermann 2009, unpublished observations) and subsequently in TGFβ2 single mutants, derived from the same breeding background (this study), but not in GDNF single mutants." (PMID 29593116, 2018). "Since we found such coloboma phenotypes in both TGFβ2 and TGFβ2/GDNF mutants, but not in GDNF mutants, we found it likely that the phenotype was resulting from a TGFβ2 loss." (PMID 29593116, 2018). "Even if GDNF single KO embryos do not show a coloboma and the transcriptional analyses performed during our analyses contradict, we cannot totally rule out that an affected GDNF signalling sensitizes the system to the loss of TGFβ2." (PMID 29593116, 2018).
colon adenocarcinoma (2 papers, 2018 to 2020). "To analyze DDB2 regulation of TGFB2 in other cancer cells, we compared the expression of the TGFB2 mRNA in colon adenocarcinoma cell lines HCT116:sh-Control and HCT116:sh-DDB2 cells, and observed a 3-fold induction in HCT116:sh-DDB2 cells (data not shown)." (PMID 30410671, 2018).
congenital cataract (2 papers, 2011 to 2024). "At present, it is difficult to determine whether systemic TGFβ1 and TGFβ2 overexpression in congenital cataracts might act as a causative or concomitant factor." (PMID 22128246, 2011). "In the PBMCs of patients with congenital cataracts, the expression of TGFβ3 (Me=9395) was the highest and significantly greater than those of TGFβ1 (Me=4475, p=0.015, post hoc test) and TGFβ2 (Me=343, p<0.001)." (PMID 22128246, 2011). "In our research, the upregulation of TGFβ1 and TGFβ2 gene expression in the PBMCs of patients with congenital cataracts might suggest that the processes occurring in the lens are affected by systemic expression levels of these cytokines, especially during fetal life when the lens is vascularized." (PMID 22128246, 2011).
cyst (2 papers, 2022 to 2024). A sac-like closed membranous structure that may be empty or contain fluid or amorphous material. "Since TGFB2 expression was upregulated in ADPKD PT, cyst FR-PTC may be driving interstitial myofibroblast proliferation." (PMID 36310237, 2022). "Although a large fraction of FR-PTC did not originate from cyst-lining cells but rather injured tubules, they still expressed proinflammatory (CCL2) or profibrotic (TGFB2) molecules, suggesting that they may be contributing to interstitial inflammation and fibrosis even though they are not cystic." (PMID 36310237, 2022).